Y_RNA (Y RNA )
Gene: Miscellaneous RNA gene on chromosome 9 (70,311,607 to 70,311,701, reverse strand). Ensembl gene ENSG00000239180.
Homologues: Orthologues: chimpanzee Y_RNA (100% identical), macaque Y_RNA (95% identical). Paralogues in human: RNY4P9 (91% identical), Y_RNA (88% identical), RNY4 (87% identical), RNY4P29 (87% identical), RNY4P6 (87% identical), RNY4P30 (86% identical), RNY4P7 (86% identical), Y_RNA (86% identical), RNY4P10 (85% identical), RNY4P14 (85% identical), RNY4P19 (85% identical), Y_RNA (85% identical), and 88 more.